C1QTNF5 (C1q and TNF related 5)
Synonyms: CTRP5; DKFZp586B0621; LORD; MFRP
Tractability: Antibody: UniProt places it where antibodies can reach, with high confidence; UniProt predicts a signal peptide or a membrane-spanning region; its Gene Ontology location is reachable by antibodies, with medium confidence.
Gene: Protein-coding gene on chromosome 11 (119,338,942 to 119,340,940, reverse strand). Ensembl gene ENSG00000223953.
Subcellular location: Secreted
Gene Ontology:
Molecular function: identical protein binding; protein binding; signaling receptor inhibitor activity
Biological process: negative regulation of lipid catabolic process
Cellular component: extracellular region; plasma membrane; apical plasma membrane; bicellular tight junction; lateral plasma membrane; membrane; protein-containing complex; transport vesicle
Genetic constraint (gnomAD): Loss-of-function variants: 5 observed, 10.14 expected, observed/expected ratio (o/e) 0.49, 90% interval 0.26 to 1.04. The upper end of that interval is the gene's LOEUF score, 1.04, which puts it in group 4 of 6, group 1 being the genes least tolerant of losing a copy. Missense variants: 281 observed, 316.63 expected, observed/expected ratio (o/e) 0.89, 90% interval 0.8 to 0.98. Synonymous variants: 161 observed, 141.43 expected, observed/expected ratio (o/e) 1.14, 90% interval 1 to 1.3.
Gene-disease validity (ClinGen):
ClinGen rates the evidence that C1QTNF5 causes each of these diseases.
inherited retinal dystrophy (autosomal dominant): Definitive. An instance of retinal degeneration that is caused by an inherited modification of the individual's genome.
Homologues: Orthologues: macaque C1QTNF5 (99% identical), pig C1QTNF5 (98% identical), dog C1QTNF5 (97% identical), rabbit C1QTNF5 (97% identical), rat C1qtnf5 (95% identical), guinea pig C1QTNF5 (94% identical), mouse C1qtnf5 (94% identical), zebrafish c1qtnf5 (64% identical). Paralogues in human: C1QTNF9 (41% identical), C1QTNF9B (40% identical), C1QTNF7 (39% identical), ADIPOQ (37% identical), C1QC (37% identical), C1QTNF2 (36% identical), COL8A2 (36% identical), COL10A1 (36% identical), C1QB (34% identical), OTOL1 (34% identical), COL8A1 (33% identical), C1QL3 (32% identical), and 11 more.
Diseases named in the same sentence as C1QTNF5 in open-access papers:
C1QTNF5 is named in the same sentence as 19 diseases in open-access papers, as found by Europe PMC text mining. Sharing a sentence is not in itself a finding about the gene and the disease. The quoted sentences say what the papers report.
retinal degeneration (6 papers, 2015 to 2023). Degeneration of the retina. "In RP-0911, a novel nucleotide change in C1QTNF5 (NM_015645.3: c.489C>A), leading to the missense mutation p.Ser163Arg previously associated with Late-Onset Retinal Degeneration (LORD, #605670) was identified in the index case." (PMID 26197217, 2015). "Mutations in C1QTNF5 have been associated with late-onset retinal degeneration." (PMID 26517551, 2015).
late-onset retinal degeneration (4 papers, 2012 to 2025). Late-onset retinal degeneration is an inherited retinal dystrophy characterized by delayed dark adaptation and nyctalopia and drusen deposits presenting in adulthood, followed by cone and rod degeneration that presents in the sixth decade of life, which leads to central vision loss. "For instance, missense variants linked to late-onset retinal degeneration in C1QTNF5 occur in the C1q head domain, responsible for functional activity, while assembly into a trimeric complex is driven by a separate collagen-like domain." (PMID 40998763, 2025). "These include Sorsby’s dystrophy (TIMP3 mutation), Doyne Honeycomb dystrophy (EFEMP1 mutation), and Late-Onset Retinal Degeneration (L-ORD, C1qTNF5 mutation)." (PMID 39983974, 2025). "In human and mouse, MFRP is expressed as a dicistronic transcript together with another gene, C1QTNF5/CTRP5 (complement-1q tumor necrosis factor-related protein 5), which is colocalized with MFRP in RPE and ciliary bodies and whose mutation was shown to cause late-onset retinal degeneration." (PMID 23112574, 2012).
age-related macular degeneration (2 papers, 2011 to 2022). Age-related loss of vision in the central portion of the retina (macula), secondary to retinal degeneration. "C1QTNF5 has been identified to be associated with age-related macular degeneration (AMD), retinal degeneration or pigmental degeneration in mice." (PMID 35402469, 2022). "A single founder mutation resulting in a Ser163Arg substitution in the C1QTNF5 gene product causes autosomal dominant late-onset retinal macular degeneration (L-ORMD) in humans, which has clinical and pathological features resembling age-related macular degeneration." (PMID 22110650, 2011).
asthma (1 paper, 2023). "PhenoScanner also revealed that C1QTNF5 is associated with rs3900945 but in a trans-acting manner, rendering them less likely to bias the PDLIM4–asthma association." (PMID 37809092, 2023).
Insulin resistance (1 paper, 2013). Increased resistance towards insulin, that is, diminished effectiveness of insulin in reducing blood glucose levels. "Further research is needed to identify the role and molecular mechanism of C1QTNF5 in the development of insulin resistance." (PMID 23970879, 2013).
macular degeneration (1 paper, 2016). Loss of vision in the central portion of the retina (macula), secondary to retinal degeneration. "The role of CTRP5 encoded by C1qtnf5-Mfrp gene is not described in the brain but it is associated with macular degeneration and lipid oxidation." (PMID 28082866, 2016).
Obesity (1 paper, 2013). Accumulation of substantial excess body fat. "C1QTNF5 gene was upregulated from the microarray result of subcutaneous fat in obese Pima Indians, suggesting its possible role in developing obesity." (PMID 23970879, 2013).
retinal disease (1 paper, 2010). "known retinal disease genes (BEST1 [NM_004183], C1QTNF5 [NM_015645], CDH3 [NM_001793], LRAT [NM_004744], RDH5 [NM_002905], RDH11 [NM_016026], RGR [NM_002921], RLBP1 [NM_000326] and STRA6 [NM_022369])." (PMID 20479888, 2010).
infection (1 paper, 2011). The state of being infected such as from the introduction of a foreign agent such as serum, vaccine, antigenic substance or organism. "Initial in vitro infection of HeLa cells showed that the wild-type protein was diffusely located in the cytoplasm but most of the mutant protein was retained in the endoplasm reticulum, consistent with previous observations when C1qtnf5 is over-expressed." (PMID 22110650, 2011).
C1QTNF5 also shares sentences with these, for which no sentence is quoted: diabetes (1 paper); diabetic retinopathy (1); gastric cancer (1); Leber congenital amaurosis (1); microphthalmia (1); Onset (1); proliferative diabetic retinopathy (1); retinal dystrophies (1); retinitis pigmentosa (1); sarcoma (1).